BUB1 (BUB1 mitotic checkpoint serine/threonine kinase)
Diseases named in the same sentence as BUB1 in open-access papers (continued):
Sharing a sentence is not in itself a finding about the gene and the disease.
cancer (continued). "To evaluate the potential impact of BUB1 inhibition in MYB‐driven cancers, we treated MM MYB cells with BAY1816032, a selective inhibitor of the catalytic activity of the kinase." (PMID 38112379, 2024). "Out of these, AURKA, TOP2A, CDK1, and BUB1 were also included in the list of most frequent top NMF genes across the 24 cancer types." (PMID 37973839, 2023). "We analyzed data from the Oncomine, Gene Expression Profiling Interactive Analysis (GEPIA), and Tumor Immune Estimation Resource (TIMER) databases to study the expression profiles of BUB1/3 in different cancer tissues." (PMID 36787437, 2023). "MPS1 and BUB1 are overexpressed in several cancers and their inhibitors are clinically emerging in cancer therapy." (PMID 37514113, 2023). "BUB1 mitotic checkpoint serine/threonine kinase B (BUB1B) was found to be up-regulated in a variety of cancers, but only two previous study showed that BUB1B was overexpressed in NPC and the sample size was small." (PMID 36577966, 2022). "Function analysis of bub1 revealed cancer-promoting effects, probably via regulating several important downstream molecules, including that related to the apoptosis process and epithelial-mesenchymal transition." (PMID 36237324, 2022). "Budding uninhibited by benzimidazoles 1 (BUB1), a mitotic checkpoint serine/threonine kinase, has been reported in numerous cancer studies." (PMID 35360870, 2022). "Other scholars have demonstrated the effects of mitotic kinases such as Nek2 and Mps1 (TTK) on EMT, focusing on AuroraA, AuroraB, Bub1 and Hec1 (high expression in cancer) as potential targets for cancer therapeutic intervention through their impact on EMT." (PMID 36313710, 2022). "bub1 has been proposed as a prognostic biomarker for other cancers including non-small cell lung cancer, gastric cancer, pancreatic cancer, and adrenocortical cancer." (PMID 36237324, 2022). "The expression of bub1 was found to be able to reduce the immunosuppressive effect of these cancers." (PMID 36237324, 2022). "BUB1B (BUB1 mitotic checkpoint serine/threonine kinase B) has been reported to contribute to the initiation and development of several cancers." (PMID 35068350, 2022). "To further validate the BUB1 expression in HCC cancer stem cells, we explored the mRNA expression patterns of BUB1 in TRCs of HCC which had the same characteristics as the CSCs using established TRCs 3D enrichment methods." (PMID 35859724, 2022). "The roles of BUB1/BUB1B in cancer cells are still controversial with contradicting results from studies." (PMID 33872216, 2021). "Overexpression of CDK1, MCM2, E2F2, PLK1, CCNB1/2, BUB1, BUB1B, CDC25 has been associated with aberrant proliferation in many cancer types including HCC." (PMID 33499054, 2021). "Our data indicated that BUB1 not only mediated cancer cell mitosis but also contributed to transcriptional activation of STAT3 signaling in BCa cells." (PMID 34852826, 2021). "The MHCF1 unique mutations consisted of protein misfolding (Hsp-related genes) and acetylcholine receptor (Chrnb4 and Chrm5) genes that possibly act on cancer cell processes, and tumor suppressor (Adamts1 and Adamts5) and cell cycle (Aurkb and Bub1) genes." (PMID 34158541, 2021). "These synergistic effects are particularly drastic in highly aneuploid HeLa cells, suggesting a potential use of Bub1 inhibitors for specifically killing aneuploid cancer cells." (PMID 33717411, 2021). "BUB1, a mitotic checkpoint serine/threonine kinase, regulates chromosome segregation, and indicates a poor clinical outcome in many cancers." (PMID 33061942, 2020). "Among these genes, BUB1 was reported as a key regulator in multiple cancer progression, including HCC, and was selected as the downstream target of DUXAP8." (PMID 32849765, 2020). "With BUB1, a subset of proteins involves in the regulation of checkpoint and a complex process of mitosis, in order to render cancer cell to keep proliferative capacity." (PMID 32206083, 2020).
cancer (continued). "Recent research indicated that BUB1 functioned as an oncogene in different tumors, in that it promoted cancer cell proliferation and invasion." (PMID 32518584, 2020). "They depleted BUB1 using shRNAs reduces cancer stem cell potential of the MDA-MB-231 BC cell line, leading to inhibited formation of xenografts in immunocompromised mice." (PMID 33285689, 2020). "It has been noted that over-expressed BUB1 is related to several cancers and their worse clinical prognosis." (PMID 31010415, 2019). "For example, TPX2, a microtubule-binding protein, is a hub gene in all 8 cancer types, while EXO1 and BUB1 are hub genes in 5 cancer types." (PMID 31179925, 2019). "In a recent meta-analysis of gene expression studies of prognostically relevant gene expression across cancers BUB1 was found to be a prognostic marker specifically in GC." (PMID 29100315, 2017). "For instance, SMC1A, CDC20, SMAD3 and BUB1 are all example AbG-0.5 kb genes known to promote cell cycle progression and proliferation in various cancer cell types." (PMID 24086155, 2013). "Studies have shown that up-regulation of CDC6, CDC 20, CDC25 family and Bub1 has relationship with human cancers." (PMID 23738901, 2013). "Compared to BUB1, a larger number of BUBR1 mutations associated with cancer have been reported to date." (PMID 20888775, 2011). "Structural information allows the mapping onto the protein surface of some of the BUB1 and BUBR1 mutations that have been associated with chromosome instability and cancer progression." (PMID 20888775, 2011). "In human cells, defects in the mitotic checkpoint proteins BUB1 and BUBR1 have been associated with various classes of cancer." (PMID 19141287, 2009). "Indeed, flow cytometry-based cell cycle profiling indicated a pronounced G2/M arrest with a concurrent accumulation in the S phase in BUB1-depleted cancer cells, particularly prominent in H2452 cells." (PMID 40180891, 2025). "Additionally, the interaction of BUB1 mRNA with RNA-binding proteins that trigger the transcription activity as SRSF family proteins suggests an important role of the BUB1 expression in cancer progression." (PMID 40723917, 2025). "Our interactome assay reveals that BUB1 could be regulated by transcription factors and molecules, such as non-coding RNAs, all involved in cancer development." (PMID 40723917, 2025). "This approach unveiled cancer cell-selective hits such as BUB1, CDK2, and VPS37A." (PMID 40180891, 2025). "The significance of BUB1 as a key driver in cancer progression is an evolving field of interest." (PMID 40180891, 2025). "Our results showed sensitivity to cisplatin and carboplatin in most cancers with high BUB1." (PMID 38396175, 2024). "Mutations in BUB1 and BUB1B genes have been identified in cancer." (PMID 39048649, 2024). "Increased expression of BUB1 is associated with resistance to DNA-damaging agents (i.e. radiotherapy and some chemotherapies) and we have shown that BUB1 inhibition reduces invasion and migration in cancer cell lines through direct interaction with TGFβ receptors." (PMID 38863037, 2024). "Finally, we performed a differential expression analysis between patients with high levels of BUB1 versus low levels of BUB1 for each cancer site of the TCGA cohort." (PMID 38396175, 2024). "BUB1 and BUBIB exhibited high frequencies of gene changes (mainly mutations, > 5%) in cancer." (PMID 39048649, 2024). "In eukaryotes, BUB1, a protein kinase from the SAC family, monitors chromosomal segregation during mitosis, which indicates that BUB1 dysregulation may lead to chromosomal instability and eventually cancer development." (PMID 37439040, 2023). "Overall, these results suggest that BUB1 is highly expressed in most cancer cells, including LUAD." (PMID 36787437, 2023).
cancer (continued). "In this study, we addressed this issue by identifying the transcriptional and protein expression patterns of BUB1/3 based on the Oncomine database, The Cancer Genome Atlas (TCGA) database, the Genotype-Tissue Expression (GTEx) database and the human protein atlas (HPA)." (PMID 36787437, 2023). "Thus, a reasonable conclusion can be drawn that BUB1 can not only regulate the cell cycle of CSCs but also influence the cellular stemness-related pathway to promote cancer progression and enhance the stemness capacity." (PMID 35859724, 2022). "Among them, BUB1 and EXO1 were associated with patient survival of all three cancers of interest." (PMID 35757968, 2022). "BUB1 Mitotic Checkpoint Serine/Threonine Kinase B (BUB1B) is an essential component of the mitotic checkpoint, and its high expression is thought to be associated with the progression and recurrence of several cancers." (PMID 35677427, 2022). "Or, the BUB1 expression level was higher in CSCs than in normal cancer cells." (PMID 35859724, 2022). "The seven DEGs (AURKA, BUB1, CDC6, MAD2L1, NDC80, ZWINT, and TIMELESS) coexpressed only in the LC&OC coexpression network have been associated with the acquisition of the hallmarks of cancer." (PMID 36101460, 2022). "We also evaluated the relationship between the expression of BUB1 in Pan-cancer and prognosis." (PMID 35769782, 2022). "As a mitotic checkpoint serine/threonine kinase, BUB1 is related to tumorigenesis in many cancers." (PMID 33767726, 2021). "In the end, the molecular function of Cdc20 in pan-cancer analysis indicated that BUB1, CCNA2, CCNB1, CDK1, MAD2L1, and PLK1 might play a critical role in its oncogenic function." (PMID 34527589, 2021). "Cluster 1 has the maximum score 27.676, with 38 nodes and 512 edges, including known cancer-related genes, such as BUB1 (mitotic checkpoint serine/threonine-protein kinase BUB1), CDC20 (cell division cycle protein 20 homolog), and PLK1 (serine/threonine-protein kinase PLK1)." (PMID 34512870, 2021). "Finally, we discuss the involvement of Bub1 in human diseases, especially in cancer, and the potential of using Bub1 as a drug target for therapeutic applications." (PMID 33717411, 2021). "BUB1 is upregulated in various types of human cancers, but the molecular function of BUB1 in promoting the occurrence and development of BCa has remained unknown." (PMID 34852826, 2021). "Aberrant expression of BUB1 has been repeatedly reported in various cancers." (PMID 32781708, 2020). "The oncogenic function of BUB1 in cell proliferation is unclear among cancer types." (PMID 32781708, 2020). "BUB1 mitotic checkpoint serine/threonine kinase (BUB1), BUB1 mitotic checkpoint serine/threonine kinase B (BUB1B), both of them play a central role in mitosis which are reported associated with aneuploidy and several forms of cancer." (PMID 33408743, 2020). "Current evidences regarding the biological role of BUB1 in cancer is contradictory." (PMID 30822312, 2019). "However, mutations in the mitotic checkpoint gene budding uninhibited benzimidazole 1 (BUB1) can induce CIN in cancer cell lines, but the frequency of Bub1 mutations in primary cancer tissues is low1." (PMID 29549256, 2018). "The role of BUB1 as a prognostic marker depends on the origin of the cancer." (PMID 29100315, 2017). "Interestingly, this effect wasnot unique to BUB1 since high-degree hubs generally exhibited asignificant skew towards increased gene expression in cancer." (PMID 25919796, 2015). "Consistent with expectations, canonical luminal genes such as ESR1, GATA3, FOXA1, TFF1 and IGF1R were higher in ER+ samples compared to triple negative samples, while proliferation and mesenchymal genes such as SPRY2, SNAI2, FOSL1, MET and BUB1 were higher in triple negative cancers." (PMID 24520381, 2014).
cancer (continued). "These kind of abnormality could be generated by alterations in checkpoint genes (Bub1, BubR1, Bub3, Mad2) such as the heterozygozity observed both in human cancer cells and patients with the rare recessive disorder mosaic variegated aneuploidy." (PMID 21483691, 2011). "Although studies on BUB1 and BUBR1 mutants have suggested that cancer formation is linked to a weakened SAC, the precise roles of these mutants in tumor formation remain unclear." (PMID 20888775, 2011). "Our functional studies in vivo suggest the Hs-BUB1 mutations E36D, A130S, and H151D, which contribute to chromosome instability in cancer cells, impaired the SAC through a mechanism that is not dependent of the direct interaction between Hs-BUB1 and Blinkin." (PMID 19141287, 2009). "Therefore, BUB1 expression might serve as a biomarker in cancer, although comprehensive analyses of BUB1 across malignancies are lacking." (PMID 38396175, 2024). "In BC, BUB1 is essential in preserving cancer stem cells, and its upregulation could be a promising prognostic biomarker related to poor prognosis in several cancer types, including BC." (PMID 39061186, 2024). "Therefore, we hypothesised that BUB1 expression could be a predictor of drug responses in cancer, with the potential to extend beyond the reported relationships with taxanes and DNA damaging compounds." (PMID 38396175, 2024). "It means BUB1-targeted cancer stem cell therapy may represent potential treatment strategies." (PMID 35859798, 2022). "Moreover, the pan-cancer analysis of the molecular function of Cdc20 indicated that BUB1, CCNA2, CCNB1, CDK1, MAD2L1, and PLK1 might play a critical role in interaction with Cdc20." (PMID 34527589, 2021). "It worth noting that for LIHC, combinations of prognostic values of SNHG20 lncRNA and BUB1 mRNA, and also SNHG12 lncRNA and TMEM164 mRNA (associated with reduced OS with worse prognosis), could strengthen the predictive value of these markers for this cancer." (PMID 35140741, 2021). "Therefore, BUB1 plays a significant role in the progression of many types of cancers in different ways, but it has been poorly investigated in the crosstalk between stromal cells and cancer cells." (PMID 34298705, 2021). "CCNB2 and BUB1 might be involved in the cancer stem cells to promote LUSC progression." (PMID 32411535, 2020). "However, BUB1 has been reported to serve differing roles in different types of cancer." (PMID 32269624, 2020). "One reason for the different roles of BUB1 in different types of cancers may be because of differences in expression level: BUB1 promotes cell death in response to chromosomal missegregation and acts to suppress spontaneous tumorigenesis in knockout and hypomorphic mouse model systems population." (PMID 29100315, 2017). "Thus, we investigated whether reduced CSC potential of Bub1-depleted MDA-MB-231 or MCF7 cells results in sensitization to anti-cancer therapies." (PMID 26522589, 2015). "Therefore, BUB1 gene seems to modulate the expression of tens or hundreds of genes suggesting that it might allow undifferentiated cancer cells to overcome apoptotic checkpoints favoring aberrant progression through mitosis." (PMID 24758163, 2014). "Furthermore, given the potential benefit of targeting the SAC as a novel approach in anticancer therapy, the BUB1 and BUBR1 structures should be important in structure-guided drug design and the development of animal models that harbor cancer-derived mutations." (PMID 20888775, 2011). "Pan‐cancer co‐expression analysis by the ENCORI database revealed that there was a positive correlation between KIF20A and BUB1 mRNA levels in CC tissues." (PMID 40914946, 2026).
cancer (continued). "Experiments have shown that BUB1 and BUB1B can promote cancer cell proliferation and are promising therapeutic targets 23-25." (PMID 40657363, 2025). "BUB1 and BUB1B expressions were significantly higher in EC in all cancer stages (P < 0.01), with higher expression in middle to late stage cancer than early-stage cancer." (PMID 39048649, 2024). "By elucidating the role of BUB1 in regulating ferroptosis and GEM resistance, our study provides valuable insights into the development of malignant tumors such as PC and offers potential clues for the development of novel therapeutic strategies." (PMID 38672622, 2024). "SCL/TAL1 interrupting locus (STIL) promotes proliferation, invasion, and cancer progression by regulating the expression of CDK1, CCNB2, CDC20, CCNA2, BUB1, and AURKB." (PMID 36661515, 2023). "The results showed that the protein expressions of BUB1 (P < 0.001), BUB1B (P = 0.025), CCNA2 (P < 0.001), and CDCA8 (P = 0.002) were significantly up-regulated in the cancer tissues." (PMID 37853361, 2023). "To further explore the role of BUB1 in cancer progression, we performed a pan-cancer study from the TCGA cohorts using TIMER2.0 and unveiled that BUB1 was upregulated in numerous cancers." (PMID 35859724, 2022). "Two ceRNAs (BUB1 and EXO1) from the BRCA‐COAD‐UCEC and the RRM2 from PRAD‐COAD‐UCEC were prognostic in all three cancer types included in the combination of interest." (PMID 35757968, 2022). "Both BUB1 and BUB1B genes were identified as shared ceRNAs across more than two HD cancers of interest." (PMID 35757968, 2022). "At present, many studies have shown that the hub genes CDC20, CDK1, BUB1, CCNB1, and BUB1B identified in our PPI network are involved in cancer progression." (PMID 35664322, 2022). "Skewed genes include a number of additional factors with established roles in cancer (e.g., BMP8A and BUB1), as well as others." (PMID 34944895, 2021). "Our study found that in ceRNA networks of LIHC, combination of prognostic values of SNHG20 lncRNA and BUB1 mRNA, and also SNHG12 lncRNA and TMEM164 mRNA (associated with reduced OS with worse prognosis), could be used as collective prognostic values for this cancer." (PMID 35140741, 2021). "AURKA and AURKB also consistently scored high across every cancer cohort, as did other cell-cycle- and mitoses-related kinases (BUB1B, BUB1, CDK1)." (PMID 33205077, 2020). "Normalization of DNMTs and UHRF1 to other markers of cancer cell proliferation, including PLK1 and BUB1, provided similar results as seen with MKI67 normalization." (PMID 32213861, 2020). "Taken together, these data suggest that BUB1, STAG2, SMC3, and THOC1 function in cell growth, proliferation, and tumorigenesis and thus play crucial roles in cancer development." (PMID 32518584, 2020). "Specifically, multiple cancers exhibit gene down regulation involving CCNB1 and BUB1, highlighting the relationship between a disrupted spindle assembly checkpoint and tumour formation." (PMID 29618387, 2018). "We identified consistently upregulated genes (such as E2F1, EZH2, FOXM1, MYBL2, PLK1, TTK, AURKA/B and BUB1) and consistently downregulated genes (such as SCARA5, MYOM1, NKAPL, PEG3, USP2, SLC5A7 and HMGCLL1) across various cancers." (PMID 28427185, 2017). "Among the module genes, BUB1, GATM, PLCE1, NEGR1, PTGER3 and SH3RF2 were differentially expressed in three or more cancer tissues." (PMID 28694494, 2017). "We have identified a number of protein kinase genes which are upregulated commonly in cancers and are involved in the cell cycle regulation such as PLK1, TTK, BUB1, BUB1B, and PKMYT1." (PMID 28427185, 2017). "In fact, cancer cells quite frequently misregulate the expression of one or more critical SAC protein including Mad2, Bub3, Bub1, and BubR1." (PMID 27869759, 2016). "In this study, the expression levels of CDC20, BUB1, MCM2, and cyclin B1 were upregulated in the 3 and 10 μmol/l genistein groups, indicating the promoting effects of genistein on cancer cell proliferation." (PMID 25385471, 2015).